SST (somatostatin)
Diseases named in the same sentence as SST in open-access papers (continued):
Sharing a sentence is not in itself a finding about the gene and the disease.
depression (62 papers, 2011 to 2026). "According to the literature, our findings suggest that HAND is associated with depression, probably due to changes in brain structure, somatostatin dysregulation, and increased levels of inflammatory cytokines." (PMID 38541857, 2024). "Whereas cortical layer SST expression loss in depression was more severe in women than in men10,77, imaging of SST expression selectively within SST interneurons showed strong reductions in both men and women in depression." (PMID 38396202, 2024). "Reduced cortical inhibition by somatostatin-expressing (SST) interneurons has been strongly associated with treatment-resistant depression." (PMID 37036854, 2023). "Somatostatin (SST) neurons have been implicated in a variety of neuropsychiatric disorders such as depression and anxiety, but their role in substance use disorders, including alcohol use disorder (AUD), is not fully characterized." (PMID 34112959, 2021). "With regard to depressed mood, modulation of cortical somatostatin interneurons causally influences anxiety- and depression-like behavioral phenotypes in rodents." (PMID 32514083, 2020). "Reduced inhibition by somatostatin-expressing interneurons is associated with depression." (PMID 38396202, 2024). "Reduced somatostatin-expressing interneuron (SST) inhibition has been implicated in depression." (PMID 37036854, 2023). "Somatostatin and clock genes also have been implicated in depression, suggesting that these molecules may represent key converging pathways involved in contextual memory processing in substance use and major depression." (PMID 36161151, 2022). "Furthermore, reduced expression of SST is a hallmark of various neurological disorders, including Alzheimer's disease and depression." (PMID 33742131, 2021). "Thus, it remains unclear whether the sex difference in bulk SST expression would translate to functional differences in loss of SST interneuron inhibition in depression, and thus difference in predicted dose of α5-PAM." (PMID 38396202, 2024). "In addition, somatostatin is associated with depression and responsiveness to drug treatment." (PMID 38698013, 2024). "Multiple studies indicate that perturbed SST-signaling, and a loss of SST-positive neurons are both linked to elevated depressive-like/anxiety-like behaviors, and vulnerability of SST neurons to damage has also been suggested in the context of major depressive disorder." (PMID 33622703, 2021). "In addition, HIV replication in the Central nervous system (CNS) causes depression via the modification of brain structures, somatostatin dysregulation and increased inflammatory cytokines, as well as lowering cognitive reserve and impairing cognitive function directly and via co-infection." (PMID 30744034, 2019). "Beyond SCZ, dysregulation of PVALB-, SST-, and VIP-expressing interneurons has been implicated in a range of neuropsychiatric and neurodegenerative conditions including bipolar disorder, major depression, autism spectrum disorder, and Alzheimer’s disease." (PMID 41159096, 2026). "Given the substantial heterogeneity of GABAergic neurons, future studies are required to elucidate the roles of specific subtypes, such as SST+ and PV+ neurons, in the context of depression." (PMID 40530388, 2025). "Recent studies implicate reduced somatostatin (SST) interneuron inhibition in depression, and new pharmacology boosting this inhibition via positive allosteric modulators of α5-GABAA receptors (α5-PAM) offers a promising effective treatment." (PMID 39729407, 2024). "Depression severity ranged from 0 to 40% reduced SST-mediated synaptic and tonic inhibition onto all cell types in the microcircuit." (PMID 39729407, 2024). "In major depressive disorder, there is also a decrease in the number and density of somatostatin-expressing neurons in the hippocampus." (PMID 39055257, 2024).
depression (continued). "Inhibition from somatostatin-expressing (SST) interneurons is reduced in depression, and new pharmacology (α5-PAM) can selectively recover this inhibition to healthy level." (PMID 39729407, 2024). "Recent studies showed a marked reduction in SST expression by SST interneurons in post-mortem tissue of depression patients, across all layers of the prefrontal cortex (PFC) and anterior cingulate cortex–key regions implicated in depression." (PMID 37036854, 2023). "Briefly, we have estimated reduction of SST interneuron synaptic and tonic inhibition conductance from gene expression data as supported by the co-localization and co-release of GABA and SST pre- and post-synaptic, and by rodent animal models of depression." (PMID 37036854, 2023). "There is growing evidence that reduced cortical inhibition plays a mechanistic role in depression and treatment-resistant depression, especially inhibition mediated by somatostatin-expressing (SST) interneurons." (PMID 37036854, 2023). "A consistent association was noted between principal neuroimaging findings in individuals with depression and downregulated genetic markers for cortical somatostatin-expressing GABAergic interneurons and astrocytes." (PMID 37365161, 2023). "Other disorders such as Alzheimer’s and aging that show changes in SST interneuron inhibition involve other key changes such as cell and synapse loss, therefore the altered inhibition may play a less central or less consistent role in these conditions than in depression." (PMID 37036854, 2023). "In this study, we identified EEG biomarkers of microcircuit effects due to reduced SST interneuron inhibition, as estimated from gene expression changes in depression." (PMID 37036854, 2023). "Studies have demonstrated that somatostatin and serotonin influence the hypothalamus-pituitary-thyroid axis, which links hypothyroidism to depression." (PMID 36003348, 2022). "Our findings represent the first evidence for altered somatostatin and clock gene expression in the hippocampus of subjects with substance use disorder and subjects with major depression." (PMID 36161151, 2022). "Given preclinical evidence that the brain SST system has profound anxiolytic and anti-depression effects, this system has therapeutic potential for treating neuropsychiatric disorders." (PMID 35800635, 2022). "We identified decreased expression of somatostatin in subjects with substance use disorder and in subjects with major depression." (PMID 36161151, 2022). "Preclinical data has shown that hippocampal PV or SST interneurons are vulnerable to psychosocial stressors, thus PV and SST deficits are frequently observed pathological features in depression and other neurological disorders with mood disturbances." (PMID 33619236, 2021). "Mental depression and cocaine addiction were enriched in SST-positive interneurons, whereas unipolar depression and major depression were enriched in CRH-positive interneurons." (PMID 33504954, 2021). "Global genetic upregulation of SST neurons reduces anxiety-like and depression-like behavior in mice, with site-specific manipulations of PL SST neurons having a similar effect." (PMID 34112959, 2021). "Many researchers regard neuropeptide systems (corticotropin-releasing factor, neuropeptide Y, galanin, vasopressin, substance p, somatostatin, etc.)as modulators of the behavioral states observed in mood disorders such as depression." (PMID 33436036, 2021). "Other neuropeptides with lower expression in depression are somatostatin (SST) and cholecystokinin (CCK)." (PMID 33589676, 2021). "Global genetic upregulation of SST neuronal function reduces depression- and anxiety- like behaviors in male and female mice, and deficits in SST expression are seen in the amygdala of postmortem samples of MDD patients." (PMID 32536856, 2020). "Based on evidence that SST interneurons are altered in depression, we then determined the effects of chronic stress on this interneuron subtype." (PMID 31712551, 2019).
depression (continued). "Recent evidence suggest that somatostatin contributes to the pathology of anxiety and depression, levels of this GABAergic marker being low in cerebrospinal fluid and induced pluripotent cells of PD patients." (PMID 31736763, 2019). "The involvement of SST dysregulation in affective disorders was suggested due to the low concentration of SST recorded in the cerebrospinal fluid of patients with depression." (PMID 29713785, 2018). "Recently, it has been demonstrated that SST-positive GABAergic interneurons are involved in the pathology of major depression, with a reduced expression of SST observed in the post mortem brains of patients." (PMID 29713785, 2018). "It has been demonstrated that SST is downregulated at the mRNA level and at the precursor protein level in the anterior cingulate cortex and dorsolateral prefrontal cortex of depression patients." (PMID 29713785, 2018). "Exposing nocturnal rats to a short photoperiod reduced anxiety- and depression-like behaviors and produced a switch from somatostatin to dopaminergic neurons in hypothalamic brain regions that receive input from the SCN." (PMID 29230328, 2017). "A long photoperiod had the opposite effect, increasing anxiety- and depression-like behaviors and producing a switch from dopaminergic to somatostatin neurons in the hypothalamus." (PMID 29230328, 2017). "Since the previously obtained data suggested the role of SST in stress and depression, we decided to measure specific binding of [125I]Tyr3-Octreotide." (PMID 26462807, 2016). "Further research is needed to understand the mechanisms of depressive-like behavior from this refractory depression model, especially the implications for other subpopulations of GABAergic interneurons including somatostatin- and NPY-positive neurons." (PMID 24671607, 2014). "In concert, these findings suggest a GABA/SST-related cellular phenotype of reduced dendritic inhibition in depression." (PMID 24062698, 2013). "Here, we summarize the current literature on deficits in somatostatin, an inhibitory modulatory neuropeptide, in major depression and other neurological disorders that also include mood disturbances." (PMID 24058344, 2013). "In this work, we showed in silico that α5-PAM therapeutic doses, which effectively recover cortical microcircuit EEG, spiking activity and function, can be predicted from simulated EEG biomarkers of depression severity in terms of reduced SST interneuron inhibition." (PMID 39729407, 2024). "We previously showed in silico that α5-PAM would recover cortical activity, function and EEG spectral profile in detailed models of human depression microcircuits with reduced SST interneuron inhibition, and we highlighted EEG biomarkers that can monitor α5-PAM efficacy." (PMID 39729407, 2024). "Furthermore, somatostatin and serotonin, known modulators of the hypothalamic-pituitary-thyroid axis, establish a connection between thyroid function, depression, and suicide." (PMID 38903642, 2024). "A decrease in SST expression in the cortex is observed in neurodegenerative and psychiatric disorders such as Alzheimer’s disease, Parkinson’s disease, Huntington’s disease, major depressive disorder, bipolar disorder, and schizophrenia." (PMID 35800635, 2022). "It is unclear whether the inhibitory synaptic properties of SST interneurons are altered in depression and whether scopolamine can reverse these changes." (PMID 36713928, 2022). "Evidence suggests that somatostatin deficits are involved in depression pathophysiology." (PMID 36297687, 2022). "In Subgroup 4, endogenous, neurotic, and syndromic form of depression, similar to mental depression observed in Subgroup 1, were enriched in SST interneurons, whereas those with bipolar disorder were enriched in Parvalbumin (PV)-positive and CRH-positive interneurons." (PMID 33504954, 2021).
depression (continued). "However, in a mouse model of depression, increasing SST+ interneurons’ excitability via cell type-specific knockout the γ2 GABA receptor subunit reduces anxiety- and depression-related behaviors." (PMID 34588960, 2021). "Interestingly, individuals with major depression have reduced numbers of somatostatin-expressing neurons (a population of GABAergic interneurons playing a key role in memory), and this reduction is exacerbated in women." (PMID 34512283, 2021). "This suggests that augmenting the function of SST+ interneurons may be sufficient to rescue depression-like behaviors." (PMID 34588960, 2021). "The current study aimed to replicate previously published findings of abstinence-induced depression in both male and female rodents, and to understand the role SST neurons throughout the brain may play in this phenotype." (PMID 32536856, 2020). "The purpose of the present study was to find whether chronic mild stress (CMS), an animal model of depression, affects the SST receptors in the rat brain and pituitary, as well as the level of SST in plasma." (PMID 26462807, 2016). "The purpose of the present study was to find whether chronic mild stress (CMS), an animal model of depression, alters the SST receptors in the rat brain and pituitary as well as the level of SST in the plasma." (PMID 26462807, 2016). "Furthermore, these local cell circuit-based findings introduce a new role for somatostatin in depression, which is distinct from its previously investigated role in the regulation of the HPA axis." (PMID 24058344, 2013). "The interaction between SST interneurons and pyramidal neurons’ apical dendrites leads to synaptic and extrasynaptic inhibition, suggesting that aHF-rTMS could exert beneficial inhibitory effects on depression symptoms." (PMID 39417327, 2024). "Thus, understanding the functions of SST neurons may provide mechanistic insight into the neurobiology of depression." (PMID 36297687, 2022). "Altered diurnal rhythms of the anxiolytic neurotransmitter somatostatin were also reported in the amygdala of subjects with BD, with decreased levels of somatostatin occurring in the morning, coinciding with reported increased severity of anxiety and depression." (PMID 34054408, 2021). "We utilized our previous detailed computational models of human depression microcircuits with reduced SST interneuron inhibition and α5-PAM effects, to simulate EEG of individual microcircuits across depression severity and α5-PAM doses." (PMID 39729407, 2024). "SST interneuron cell loss may also lead to similar outputs as SST interneuron inhibition loss, but we note that only a loss of SST expression has been observed in depression and not a loss of cells." (PMID 39729407, 2024). "Thus, reduced SST interneuron inhibition in depression may affect EEG low-frequency power." (PMID 37036854, 2023). "Relatedly, including deeper layers will provide insight on laminar interactions mediated by SST interneurons and their contributions to EEG in health and depression." (PMID 37036854, 2023). "The levels of somatostatin and GABA in cerebrospinal fluid are often reduced in patients with major depression and they recover when MDD symptoms subside." (PMID 35204812, 2022). "Some of the common down genes in maternal C57 mice and depression were for the MAP kinase pathway and some of the common down genes included: FOS, EGR1, DUSP1, BDNF, NR4A1, NR3C1, the neuropeptide somatostatin (SST), and one of the its receptors, SSTR2." (PMID 34997033, 2022). "The involvement of somatostatin (SST) and its receptors in the pathophysiology of depression and stress has been evidenced by numerous studies." (PMID 26462807, 2016). "Relatedly, silencing SST interneuron inhibition led to depression symptoms, and novel therapeutic compounds acting via positive allosteric modulation of alpha-5-GABA-A (α5-GABAA) receptors targeted by SST interneurons resulted in pro-cognitive and anxiolytic effects." (PMID 37036854, 2023).
depression (continued). "A decrease in the signal pathway of SST + neurons/α5-GABA receptor pathway will lead to cognitive dysfunction, representing a new treatment target for treating cognitive disorder symptoms of depression." (PMID 35664493, 2022). "Despite the clear correlation between SST neuronal markers and their function in MDD, both in the human and preclinical animal literature, thus far SST neurons have been poorly investigated in the context of AUD and depression-like phenotypes seen during withdrawal from alcohol." (PMID 32536856, 2020). "Here, we provide further evidence supporting the role of cortical GABAergic interneurons, mainly somatostatin- and parvalbumin-expressing cells, required for the optimal E:I balance in the PFC and discuss how the malfunction of these cells can result in depression-related behaviors." (PMID 30914923, 2019). "Nonetheless, there is still a lack of studies exploring the role of somatostatin in anxiety and depressive disorders in PD." (PMID 31736763, 2019). "Somatostatin (SST), a marker of a subtype of GABA interneurons that preferentially target the distal dendrites of excitatory pyramidal cells, is more robustly reduced in female subjects with depression." (PMID 27660699, 2016). "Polygenic somatostatin interneuron markers were most expressed in the subgenual anterior cingulate, medial PFC, anterior insula, and temporal lobes, coinciding with brain areas where imaging studies confirmed cortical thinning and aberrant connectivity in individuals with depression." (PMID 37365161, 2023). "Abnormalities of GABA interneurons, particularly the somatostatin (human, SST; mouse, Sst) subtype, have been reported in postmortem brains of depressed subjects and include sex differences that could explain the increased incidence of depression in women." (PMID 31712551, 2019). "Furthermore, this study did not demonstrate whether somatostatin changes are specifically related to either suicidality or depression but only that somatostatin changes are related to clinical symptomatic recovery in suicidal patients." (PMID 23986909, 2013). "These current data suggest that ghrelin receptor, but not somatostatin system, is involved in the actions of CST-14 in depression process." (PMID 30072893, 2018). "However, the study utilized an average reduced SST interneuron inhibition as a model of depression microcircuits and EEG effects, and did not consider varying depression severity level." (PMID 39729407, 2024). "The pathway consists of 5-hydroxytryptamine (5-HT) projections from the dorsal raphe nucleus to somatostatin (SOM)-expressing and non-SOM interneurons in the central nucleus of the amygdala, which continue to extend directly towards the lateral habenula, an area known to be involved in depression." (PMID 35545623, 2022).